FOXP3 (forkhead box P3)
Diseases named in the same sentence as FOXP3 in open-access papers (continued):
Sharing a sentence is not in itself a finding about the gene and the disease.
tumor (continued). "Notably, the prognostic values of tumor-cell FOXP3 expression were determined according to FOXP3 localization; nuclear FOXP3 expression was significantly associated with improved OS (HR: 0.13; 95% CI: 0.02–0.95; P=0.016)." (PMID 24649219, 2013). "Cytoplasmic FOXP3 expression in tumor cells was significantly associated with larger tumor size (P=0.035) and presence of metastatic lymph nodes (P=0.015), whereas nuclear FOXP3 expression in tumor cells was significantly associated with ER positivity (P=0.003)." (PMID 24649219, 2013). "Indeed, while initial studies associate the tumor infiltration of FOXP3+T cellswith a worse prognosis, other reports associate the infiltration of FOXP3+T cells with a better survival or with better locoregional control of the tumor." (PMID 23977174, 2013). "In addition, the tumor-infiltrating Foxp3+ T-cells express high levels of memory/tumor-associated CCR8 and CXCR4 receptors, and antigen priming is required for the induction of this trafficking receptor phenotype." (PMID 24133490, 2013). "To determine whether the reduction of Foxp3 expression and inhibition of tumor growth induced by entinostat was associated with increased immune response, we examined IFN-γ induction." (PMID 22303460, 2012). "The FoxP3+ T cells in other tumor types were similarly deficient in expression of CCR7 and CD62L." (PMID 22292042, 2012). "The reason that TIM-3 is highly expressed in FOXP3+CD4+ TILs might be due to constant stimulation by tumor associated antigens within the tumor site." (PMID 22363469, 2012). "We investigated the migration requirement and stability of tumor-associated FoxP3+ T cells." (PMID 22292042, 2012). "FOXP3+ Tregs have a pivotal role in maintaining immune system homeostasis through their ability to suppress immunologic responses, including tumour immunity against tumour-associated antigens." (PMID 21730981, 2011). "Furthermore, the high density of FOXP3+ tumor infiltrated lymphocytes (TILs) is associated with improved progression-free survival (PFS) in ENKTL patients (p < 0.05)." (PMID 22151904, 2011). "In addition as cortisol can control the production of IL-10 and TGF-β, these cytokines have been linked to the establishment of immune suppression in the tumor microenvironment by aiding in the expansion of FoxP3+ regulatory T cells (Treg)." (PMID 20946663, 2010). "Because regulatory T cells are associated with tumor tolerance, we hypothesized that a similar increase in Foxp3+ regulatory T cells in lung tissues may be associated with tobacco carcinogen-induced tumorigenesis." (PMID 19330036, 2009). "Induction of lung tumors and tumor-associated Foxp3+ cells by NNK was also dose-dependent." (PMID 19330036, 2009). "Thus, NNK and rapamycin reciprocally regulate Foxp3+ cells in lung tissues prior to tumor development, suggesting that lung-associated Foxp3+ cells contribute to tumorigenesis." (PMID 19330036, 2009). "The increased inflammatory response in lungs from scurfy mice that occurred as a result of loss of Foxp3+ cells may have decreased tumor growth through elimination of nascent tumors." (PMID 19330036, 2009). "To evaluate whether curcumin enhances T cell activation and cytotoxic capacity while improving the tumor microenvironment, we performed PD-L1/PD-1 blockade assay and analyzed factors associated with T cell activation and cytotoxicity (FOXP3, GZMB, c-caspase-3 and IFN-γ)." (PMID 41522360, 2026). "In notable contrast to our observations in healthy adult mice — where Foxp3 degradation induced minimal transcriptional changes — loss of Foxp3 protein in tumor-bearing mice led to profound and widespread transcriptional alterations within tumor Treg cells visualized by UMAP." (PMID 40470210, 2025).
tumor (continued). "Interestingly, declining FOXP3 mRNA levels correlated with advancing tumor stages, and stage-stratified survival analysis confirmed that low FOXP3 expression in advanced stages was significantly associated with poor overall survival in both the MMA and TCGA cohorts." (PMID 40806346, 2025). "Notably, despite the limited data available on tumor expression in our study, tumors with low levels of FOXP3 mRNA and high levels of PD-L1 mRNA were associated with a more pronounced survival differences, suggesting their potential interplay in tumor immune regulation." (PMID 40806346, 2025). "Because the loss of IFNγ expression was confined to the Foxp3+ Treg population, we hypothesize that IFNγ production by fragile and instable Tregs may contribute to increased infiltration of the tumor by CD8+ T cells in FS120m-treated mice, resulting in enhanced antitumor immunity." (PMID 38995700, 2024). "Some Treg subsets, particularly those with high FOXP3 expression, have been linked to an anti-tumorigenic response, possibly due to their role in maintaining immune homeostasis and preventing overactive inflammatory responses that can contribute to tumor growth and metastasis." (PMID 38375478, 2024). "Thus, the Foxp3 + Treg population exhibited a trend toward a significant reduction in tumour density in Bach2-deficient animals reveals therapeutic targets for reversing cancer immunosuppression and is unquestionably a critical part of the molecular pathway involved in tumour immunosuppression." (PMID 38459508, 2024). "For instance, the existence of CD4+CD25+Foxp3+ regulatory T cells has been associated with unfavorable survival rates, implying that these cells might contribute to malignancy progression by dampening anti-tumor immunological defenses." (PMID 39267764, 2024). "Therefore, the influence of the deficiency of DCs on the population sizes of CD4+Foxp3+ Treg cells and Teff cells may regulate the direction of the adaptive anti-tumor immune responses that control the development of tumors." (PMID 39206204, 2024). "Tregs are a subset of CD4+ T cells that are induced by transcription factors such as FOXP3 and are responsible for autoimmune tolerance and homeostasis, suppressing the excessive immune response that causes allergic and autoimmune diseases, and promoting tumor progression." (PMID 36769116, 2023). "However, a high level of FOXP3 in tumor cells is associated with longer and disease-free survival." (PMID 37176567, 2023). "In addition, the expression of Foxp3 in Tregs may be associated with the complex interaction between various immune cells and tumor cells." (PMID 36776832, 2023). "While we detected higher levels of markers associated with effector responses, such as CD20, GZMB, and CD56 in ‘immune-rich cancer cell islet’ regions, additional expression of markers such as PD-1 and FOXP3 in the same regions may reflect mechanisms associated with tumor growth in NPC." (PMID 37046826, 2023). "Moreover, in terms of SNPs distant effect, trans‐eQTL results indicated that STAT3 expression was positively associated with Foxp3 expression in both tumor (statistics r: 0.794, β‐Score: 1.109) and higher infiltration groups (statistics r: 0.411, β‐Score: 0.484)." (PMID 36226375, 2023). "Joint decrease in IL-2 and IL-4 could be inducing a decrease in certain Tregs function after NAC, which would explain the stromal and tumor decrease in FoxP3 reported here, as well as the significant association between post-NAC expression of IL-10 and IL-17 and failure to obtain pCR." (PMID 37104271, 2023). "Overall, the immune tolerant TME in NeuT/ATTAC mice was associated with tumor-infiltrating macrophages, Foxp3+/PD-1- Treg cells as well as upregulation of the Wnt signaling pathway, which may provide further insights into the therapeutic options that may enhance immune checkpoint therapy." (PMID 36537914, 2022).
tumor (continued). "SCFAs can boost cellular metabolism and memory potential in CD8+ T cells, which may mean that SCFAs can promote a favourable tumour microenvironment in bladder cancer, in which T-cell inflamed tumours with increased FOXP3+ Treg infiltration have been associated with improved patient survival." (PMID 36175620, 2022). "Interestingly, the transcription factor Foxp3, which is a common marker for Tregs broadly linked to immunosuppression and tumor protection, showed significantly increased expression in the cold tumor subgroup." (PMID 36139700, 2022). "Our results demonstrated that FoxP3+ TILs may be associated with tumour recurrence." (PMID 33170901, 2020). "In fact, numerous studies underlined the poor prognosis of HNSCC patients with a high FoxP3+ Treg infiltration while others, such as our laboratory, rather highlighted that a high recruitment of these cells is associated with a longer overall survival and a better tumor loco-regional control." (PMID 30781400, 2019). "In addition, we found negative correlation between subsets of TILs (CD45RO+ TILs in the invasive margin area and FOXP3+ TILs in the central tumor area) and risk stratification, which confirmed the inherent association between inflammatory/immune tumor microenvironment and clinical outcome." (PMID 31616592, 2019). "Moreover, tumor-infiltrated FoxP3+ Tregs are significantly associated with poor OS of GC patients." (PMID 31417548, 2019). "In addition, a decreased CD8/FoxP3-ratio was associated with tumor progression during follow-up." (PMID 29942303, 2018). "Therefore, the percentage of Foxp3+ T cells in tumor specimens may predict a risk for intravesical recurrence." (PMID 30261082, 2018). "Transcriptional factors, which are typically associated with this process (Myc, Foxp3), were more highly expressed in metastatic cells when compared to primary tumour cells, highlighting the differential transcriptional processes of primary and metastatic tumour cells." (PMID 29440650, 2018). "Furthermore, inhibition of CD4+ Foxp3+ Treg cells could be another mechanism associated with enhanced NK cell immunity in the tumour-bearing Smad3−/− mice." (PMID 28262747, 2017). "The alanine scan program identified key residues implicated in the interaction of P60 with FOXP3 and allowed us to define a pharmacophoric model for the identification of a cyclic peptide with improved capacity to inhibit Treg cells in vitro and with anti-tumor activity in vivo." (PMID 29069740, 2017). "We identify several Th17–Treg transdifferentiation-associated transmembrane molecules on IL-17A+Foxp3+ cells that may be feasible targets to manipulate Treg cell-associated tumour immune surveillance, and complement programmed cell death protein 1 (PD1)-mediated control of T-cell activation." (PMID 28290453, 2017). "While the potential role of tumor Foxp3 as prognostic biomarker of overall survival has been previously investigated, only two studies addressed this issue and draw accordant conclusion that high Foxp3 expression was associated with poor overall survival in patients with TSCC and OHSCC respectively." (PMID 27457382, 2016). "As cytokine network in tumor microenvironment affect Tregs proliferation and function, this part of findings are consistent with the hypothesis that cancer cell-derived Foxp3 regulates the microenvironment through its association with Tregs, thereby influencing the tumor immune response." (PMID 25779374, 2015). "Collectively, these results indicate that tumor-associated macrophages could express Foxp3." (PMID 25264896, 2014). "Further analyses confirmed Foxp3 expression in macrophages by RT PCR, and studies using ribonucleic acid-sequencing (RNAseq) demonstrated a previously unknown Foxp3 messenger (m)RNA transcript in tumor-associated macrophages." (PMID 25264896, 2014).
tumor (continued). "The prognostic associations of FOXP3+ TILs could be affected by tumor microenvironment, including tumor site, histologic and molecular subtype, and different types of immune response, all of which may interactively influence clinical outcome of cancer patients." (PMID 25193543, 2014). "Indeed, the studies associating high densities of tumor-associated cells expressing TREG markers including FOXP3 with a poor prognosis in several types of human cancers are now challenged by similar studies on the very same types of cancer showing the opposite outcome." (PMID 24778636, 2014). "In addition, TGF-β induces FoxP3 thereby generating inducible regulatory T lymphocytes and exerts additional immunosuppressive functions by acting on myeloid-derived suppressor cells, tumor-associated neutrophils and tumor-associated macrophages." (PMID 24797128, 2014). "Finally, we investigated the association of CD4+Foxp3+LAP+ T cells with tumor stage." (PMID 25268580, 2014). "Some studies showed that tumor-infiltrating FOXP3+ T cells have been associated with poor prognosis, consistent with the initial hypothesis that FOXP3+Treg inhibit antitumor immunity; while other studies found that FOXP3+ T cells are associated with a favorable prognosis." (PMID 23977174, 2013). "However, cytoplasmic or nuclear FOXP3+ tumor cells may also be associated with OS, as the correlation was at ∼5% significance level, following adjustment for possible confounding factors." (PMID 24649219, 2013). "In a recent clinical trial utilizing multiple tumor-associated peptides as a therapeutic vaccine for renal cell cancer, T-cell responses of treated patients were associated with better disease control and correlated with lower numbers of FOXP3+ Treg cells prior to vaccination." (PMID 23874336, 2013). "Thus, the roles of tumor-associated FoxP3+ T cells appear to be complex." (PMID 22292042, 2012). "In conclusion, GP reduced the proportion of Treg cells and Foxp3 lowered expression in Treg cells, and up-regulated Th1/Th2 cytokine ratio in serum in the tumor bearing mice, which might partially cause the inhibition of tumor growth." (PMID 21963624, 2011). "Thus, the association between FoxP3+ cells and increased survival could potentially reflect an underlying Th17-like anti-tumor response." (PMID 19641607, 2009). "High-PBK tumors showed an immune-activated microenvironment, including increased CD4+, CD8+, and FOXP3+ T-cell infiltration, higher stromal PD-L1 expression, and higher tumor-infiltrating lymphocyte scores." (PMID 41681955, 2026). "STT3A knockdown significantly reduced tumor volume and weight and decreased FOXP3 and CD25 expression in tumor tissues." (PMID 41493695, 2026). "To further validate the immunomodulatory effects of our hydrogel-based therapy, we additionally performed immunohistochemical (IHC) staining for Foxp3+ Tregs in tumor tissues." (PMID 41424863, 2026). "In the tumor center, similar but weaker patterns are seen, and KRAS mutation is additionally linked to increased regulatory T cell (FoxP3+) infiltration, further supporting an immunosuppressive phenotype." (PMID 41596586, 2026). "After 48 h of direct co‐culture, DDKC tumor cells displayed a greater potential to differentiate activated CD4+ T cells into CD4+FoxP3+ Tregs than KC cells." (PMID 41147409, 2026). "Analysis of Tregs revealed that rBCG reduced the frequency of CD25+ FoxP3+ cells both in the spleen and in the tumor, mitigating immunosuppressive mechanisms." (PMID 41522339, 2026). "Surgical margins underwent multi-modal assessment, including histopathology (tertiary lymphoid structures), tumor burden (Pan-CK, Ki-67), molecular profiling (driver mutations, PD-L1 RNA), and immune contexture (CD8+/FoxP3+ ratio, Granzyme B)." (PMID 41727460, 2026). "Flow cytometry demonstrated a marked reduction in tumor-infiltrating CD4+CD25+Foxp3+ regulatory T cells, indicating modulation of the tumor immune microenvironment." (PMID 42192889, 2026).
tumor (continued). "Results indicated that the T cell activation markers GZMB and IFN-γ were significantly increased in the tumor, while the immunosuppressive factor FOXP3 was significantly reduced following curcumin treatment." (PMID 41522360, 2026). "To further evaluate the immunosuppressive landscape within the tumor microenvironment, we analyzed FoxP3 and CD25 expression in CD4+ T cells." (PMID 41522339, 2026). "T cells in the tumor cells (CD4+ FOXP3+ CD25+ T cells and CD8+ FOXP3+ CD25+ T cells) are immunosuppressive due to their increased secretion of inhibitory cytokines and inhibition of naïve T cell proliferation." (PMID 40563393, 2025). "The number of Foxp3+ cells in the tumor treated with the combination therapy was significantly lower than with the control vehicle." (PMID 40371846, 2025). "As regards FoxP3+ as a marker for T regulatory (Treg) cells, the perinuclear and nuclear pattern of FoxP3+ immuno-expression on tumour-infiltrating T cells was noted." (PMID 40247360, 2025). "One factor implicated in T cell dysfunction is the transcription factor FOXP3, best known for its role in Tregs, but also transiently expressed in Teff and tumor-infiltrating lymphocytes (TILs) upon activation." (PMID 40955316, 2025). "FOXP3 T allele deletion and HLA‐G polymorphism in the blood of patients correlate with higher STAT3 tumor expression and elevated IL‐4 and IL‐17 blood cytokines." (PMID 41263059, 2025). "Tumor growth was significantly attenuated in syngeneic tumor-bearing mice treated with mouse FOXP3 ASO, with a partial reduction in FOXP3 mRNA (20%–60% compared with baseline)." (PMID 39937271, 2025). "In head and neck cancers, the accumulation of Foxp3+ Tregs correlates with improved prognoses, likely reflecting their diverse functions within different TMEs (tumor microenvironment) affecting their activity in various tumor areas." (PMID 40959055, 2025). "Clinically, FOXP3+ Treg infiltration correlates with advanced tumor stage and reduces 5-year survival by 41.3%." (PMID 40510364, 2025). "Contrarily, FOXP3+ regulatory T cells contribute to a suppressive tumor microenvironment, facilitating tumor immune evasion." (PMID 40843004, 2025). "The authors reported FoxP3+ Treg as an independent prognostic factor in these samples, in combination with tumor stage and histological grade." (PMID 41511327, 2025). "Mechanistically, it reduces regulatory T cell and tolerogenic dendritic cell activity, decreases FOXP3 and IL-10 expression, and reprograms the tumor microenvironment toward immune activation." (PMID 41471273, 2025). "A single intraperitoneal injection of 5-Ph-IAA was sufficient to degrade approximately 75% of Foxp3 protein in GFP+ tumor-infiltrating TREG cells,15 hours post-injection." (PMID 40478934, 2025). "In a nutshell, more abundant CD8+ cells in either the tumor or stroma were associated with a positive treatment response, especially the CD8+PD-1+ and the CD8+FoxP3− subsets." (PMID 40422521, 2025). "T helper (CD4+) and Treg (FoxP3+) cells were very low (1–2 cells/mm2 and undetectable, respectively) in control non-tumor samples, while they were significantly more abundant in cancer samples." (PMID 40703808, 2025). "The high-risk group exhibited significantly greater infiltration of regulatory T cells (Tregs, CD4 + Foxp3+), indicative of an immunosuppressive tumor microenvironment." (PMID 40533802, 2025). "Taken together, our data suggest that CD8+ T cells alter the homing of CD4+Foxp3+ T cells into the tumor microenvironment." (PMID 40553564, 2025). "It reduces the proportion of anti-tumor Th1 cells while enhancing NF-κB activation and Foxp3 expression in naïve T cells, thereby driving their differentiation into Tregs." (PMID 41152975, 2025). "As reported in other mouse tumor models, 9D9 reduced the frequency of intratumoral FOXP3+ Tregs in an Fc-dependent manner." (PMID 40460830, 2025).